MIR29C (microRNA 29c)
Synonyms: hsa-mir-29c; MIRN29C; miRNA29C; mir-29c
Gene: MicroRNA gene on chromosome 1 (207,801,852 to 207,801,939, reverse strand). Ensembl gene ENSG00000284214.
Gene Ontology:
Biological process: miRNA-mediated post-transcriptional gene silencing
Cellular component: RISC complex
Homologues: Orthologues: chimpanzee ptr-mir-29c (100% identical), guinea pig MIR29C (100% identical), mouse Mir29c (100% identical), pig ssc-mir-29c (100% identical), macaque MIR29C (95% identical), tropical clawed frog xtr-mir-29c (83% identical). Paralogues in human: MIR29A (58% identical), MIR29B2 (56% identical), MIR29B1 (53% identical).
Diseases named in the same sentence as MIR29C in open-access papers:
MIR29C is named in the same sentence as 1 disease in open-access papers, as found by Europe PMC text mining. Sharing a sentence is not in itself a finding about the gene and the disease.
MIR29C shares sentences with these, for which no sentence is quoted: pancreatic adenocarcinoma (1 paper).